KMO (kynurenine 3-monooxygenase)
Diseases named in the same sentence as KMO in open-access papers (continued):
Sharing a sentence is not in itself a finding about the gene and the disease.
tumor (continued). "In the data set for the seven matched pairs of chromophobe RCC versus normal kidney, very similar results as for ccRCC were obtained, with expression of QPRT, KMO and HAAO being below the level of detection in tumours (with one exception)." (PMID 32390008, 2020). "Also, KMO activity may be involved in tumor immune tolerance." (PMID 32153576, 2020). "Moreover, reduction of KMO expression after its exposure to MCLs may serve as an exciting candidate in regulating the kynurenine pathway in tumour immunity and opens up the possibility that disrupting the metabolism of kynurenines may be used to design novel and more effective treatment strategies." (PMID 31434983, 2019). "However, roles of KMO in tumor,including HCC, remain hitherto unknown." (PMID 26099564, 2015). "Specifically, using co-culture models of patient autologous pDC–T–NK–MM cells, authors showed that pharmacological blockade of KMO activates pDCs and triggers both MM-specific cytotoxic T-cell lymphocytes (CTL) and NK cells` cytolytic activity against tumor cells." (PMID 37876966, 2023). "Results from the in vitro experiment comparing KMO enzyme levels in human normal liver cells and HCC cell lines showed that KMO enzyme was upregulated in HCC cells and might play a role in promoting tumour proliferation, metastasis, and invasion." (PMID 34680327, 2021). "KMO expression correlated with tumor metastasis but not age, sex, tumor location, pathology, AJCC stage, grade, or lymphovascular invasion." (PMID 33937026, 2021). "Interestingly, normal breast epithelial cells in the immediate tumour proximity also showed elevated TDO2 and KMO expression, implying that IDO1/TDO2 expressing tumours have the capability to influence KP activity in surrounding normal tissue." (PMID 26646699, 2016). "Considering that these subtypes are associated with higher rates of lymph node metastasis, elevation of the early KP enzymes TDO2, KMO and KYNU may promote tumour aggressiveness and metastasis." (PMID 26646699, 2016). "Furthermore, KMO overexpression is correlated to the enhancement of the signal transducer and activator of the transcription 3 (STAT3) and pSTAT3 genes, which are related to the proliferation, survival, invasiveness, malignancy, and metastasis of tumor cells." (PMID 34683090, 2021). "Interestingly, lower KMO mRNA expression was seen in CD4+ T-cells upon co-culture with MCLs, suggesting that KMO may play a role in determining the levels of KYNA and may also be an exciting candidate regulating the kynurenine pathway in tumour immunity." (PMID 31434983, 2019). "In our results, KMO overexpression was independent of IDO expression in CMTs, suggesting that KMO might induce tumor malignancy via a novel mechanism not involving IDO." (PMID 31186637, 2019). "No other study has investigated the role of KMO in canine tumor development." (PMID 31186637, 2019). "However, there was no significantassociation between expression of KMO and other clinicopathological parameterssuch as age, sex, HBsAg status, tumor size, Child-Pugh, and vascular invasion." (PMID 26099564, 2015). "Besides, the nonenzymatic function of KMO can promote the stability of β-catenin and the expression of pluripotency genes, thereby, promoting the proliferation, survival, invasion, and metastasis of tumor cells." (PMID 40145017, 2025).
neurodegenerative disease (19 papers, 2014 to 2025). A disorder of the central nervous system characterized by gradual and progressive loss of neural tissue and neurologic function. "An infamous example is the inhibition of kynurenine 3-monooxygenase (KMO) whose product’s (3-hydroxykynurenine: 3-HK) overproduction is known to cause several neurodegenerative diseases." (PMID 39050937, 2024). "Further supporting the association of KMO in neurodegenerative diseases is the fact that the KMO inhibitor drug, JM6, has been noted for its ability to inhibit the loss of synapses, lower microglial activation, and increase life span in an HD mouse model." (PMID 38255925, 2024). "The KMO enzyme has also been directly and considerably implicated in the pathology of neurodegenerative diseases." (PMID 38255925, 2024). "Previously, KMO had been shown to associate with pathological conditions like tumorigenesis and neurodegenerative diseases." (PMID 35235615, 2022). "Kynurenine monooxygenase KMO, as a key rate-limiting enzyme in the kynurenine pathway, has become an important target for the treatment of neurodegenerative diseases in the human body." (PMID 40630182, 2025). "Upon induction from pro-inflammatory stimuli, microglia have been known to express KMO, which leads to their production of quinolinic acid, another neurotoxin known to play a large role in neurodegenerative disease pathology." (PMID 38255925, 2024). "The therapeutic potential of targeting KMO in neurodegenerative diseases is supported by several studies published over the past ~15 years using genetic and pharmacological approaches." (PMID 31372510, 2019). "Inhibition of the enzyme kynurenine 3-monooxygenase (KMO) in the KP normalises these metabolic imbalances and ameliorates neurodegeneration and related phenotypes in several neurodegenerative disease models." (PMID 31372510, 2019). "Our results are supported by preclinical evidence that shows that the administration of KMO inhibitors counteracted the effects of neuroinflammation in various neurodegenerative diseases." (PMID 30050435, 2018). "In animal models, KMO inhibition has shown benefit in neurodegenerative diseases such as Huntington's and Alzheimer's." (PMID 28604669, 2017). "If future animal models prove to demonstrate neuroprotective effects, Ianthellamide A will not only be used to model novel KMO inhibitors, but could also possibly serve as therapy for the treatment of neurodegenerative diseases." (PMID 35011505, 2022). "Kynurenine-3-monooxygenase (KMO) is an enzyme in the neurotoxic branch of the kynurenine pathway (KP) and is a target of inhibitors with therapeutic potential against neuroinflammatory and neurodegenerative diseases." (PMID 36290320, 2022). "Cannflavin A, extracted from hemp aerial parts, was proven as a KMO inhibitor, with an IC50 = 29.4 μM, compared to the positive control Ro 61-8048 (IC50 = 5.1 μM), suggesting a possible therapeutical usage in neurodegenerative diseases." (PMID 40364401, 2025). "Kynurenine 3-monooxygenase (KMO) is a drug target for neuroinflammatory and neurodegenerative diseases." (PMID 40364401, 2025). "KMO plays a role in balancing NMDA receptor agonists and antagonists; therefore, KMO inhibitors can be applied in therapy for neurodegenerative diseases." (PMID 31186637, 2019). "The inhibition of IDO, KMO, and QPRT represents an important pharmacological target, since the kynurenines are involved in many neurodegenerative diseases." (PMID 24693337, 2014). "Miscellaneous KMO inhibitors have been developed and investigated for neurodegenerative disorders, for instance, a KMO tight-binding inhibitor, UPF 648, which is able to cross the blood–brain barrier in targeted therapies against neurodegenerative diseases." (PMID 33937026, 2021).
neurodegenerative disease (continued). "Actually, whereas KMO inhibition leads to brain 3-HK and QUIN reduction, this may provide benefits in neurodegenerative diseases; the blockade of KAT II brings about a decrease in brain KYNA but can be related to cognition-enhancing effects." (PMID 24693337, 2014).
neurological disorders (11 papers, 2015 to 2024). "All these reports indicate the need for further research concerning the use of KMO inhibitors in the therapy of neurological disorders with accompanying accumulation of KP metabolites." (PMID 34206739, 2021). "In turn, preclinical studies indicate that targeting KMO in neurological disorders is a more efficient and safe solution." (PMID 34206739, 2021). "The KMO gene involvement in neurological disorders identified in Huntington disease and schizophrenia." (PMID 29951083, 2018). "Together, the evidence suggests that KMO is positioned at a critical metabolic junction to influence the development or trajectory of a myriad of neurological diseases." (PMID 26347662, 2015). "Recent studies have shown that inhibiting the activities of de novo pathway enzymes, such as tryptophan-2,3-dioxygenase (TDO) and kynurenine-3-monooxygenase (KMO), may help alleviate specific neurological disorders." (PMID 34095234, 2021). "Neurological diseases with disrupted kynurenine metabolism – a focus on KMO regulated metabolites." (PMID 26347662, 2015). "Though proposed for therapeutic use in HD patients, the data reviewed here clearly demonstrate that treatment with an effective KMO inhibitor could potentially be beneficial to patients diagnosed with other neurological disorders." (PMID 26347662, 2015). "In addition, treatment with KMO inhibitors could be beneficial in other neurological disorders." (PMID 34206739, 2021). "KMO controlling the chief division of the KP, which directly controls downstream product quinolinic acid (QUIN) and indirectly controls kynurenic acid (KYNA), plays an important role in many diseases, especially neurological diseases." (PMID 32148781, 2020).
infection (7 papers, 2016 to 2025). The state of being infected such as from the introduction of a foreign agent such as serum, vaccine, antigenic substance or organism. "At the same time, the Kyn/Trp ratio is lower in Mf during this phase of the infection, presumably due to the enhanced activity of KMO." (PMID 35242812, 2021). "Dysregulation of IDO, KATII, and KMO mRNA levels was observed in both models of infection compared to levels in the controls." (PMID 28446679, 2017). "As such, compounding effects of direct BDV-induced and inflammation-induced regulation may contribute to the dramatic dysregulation of KMO in the adult infection model." (PMID 28446679, 2017). "In order to determine whether in vivo infection leads to persistent kynurenine-3-monooxygenase (KMO) mRNA induction, we quantitated KMO transcripts in the HC, CBLM, and STRI of NBD rats at the ages of 3, 4, 6, and 12 weeks." (PMID 28446679, 2017). "Gene expression analysis of rat brains following neonatal infection showed increased expression of kynurenine amino transferase II (KATII) and kynurenine-3-monooxygenase (KMO) enzymes." (PMID 28446679, 2017). "Paralleling trends in the CNS of these animals, we found that upstream enzymes (IDO1, KMO, and KYNU) displayed significant mRNA upregulation during at least one phase of infection, while downstream enzymes (HAAO and QPRT) were either downregulated or unchanged." (PMID 28066416, 2016).
psychiatric disorder (6 papers, 2010 to 2026). A disorder characterized by behavioral and/or psychological abnormalities, often accompanied by physical symptoms. "This activation also increases activity of the kynurenine pathway (KP) and alters expression of key KP enzymes such as indoleamine 2,3-dioxygenase (IDO-1) and kynurenine 3-monooxygenase (KMO), both major contributors in the pathology of several neurodegenerative and psychiatric disorders." (PMID 41602856, 2026). "Often termed the “neurotoxic” and “neuroprotective” branches of the KP, or alternatively the “excitatory” and “inhibitory” branches, KMO and KATs regulate the balance of QUIN:KYNA production which is important in both neurodegenerative and psychiatric disorders." (PMID 24567701, 2014).
cardiovascular diseases (2 papers, 2023 to 2024). "Several studies have investigated the role of KMO in cardiovascular diseases." (PMID 39026250, 2024).
central nervous system diseases (2 papers, 2020 to 2022). "Some researchers found that peripheral KMO deficiency might be divided into at least, two patterns, while having fewer research mechanisms besides central nervous system diseases which requires further research." (PMID 32148781, 2020). "KMO acts as a regulator of the KP, with imbalances leading to peripheral inflammation and diseases of the central nervous system." (PMID 36290320, 2022). "On the way of tryptophan catabolism and the high activity of KMO in liver and kidney (Bertazzo, Ragazzi, & Biasiolo, 2001), KMO plays a very important role and has a definite regulatory effect on peripheral inflammation and central nervous system diseases." (PMID 32148781, 2020). "Kynurenine‐3‐monooxygenase (KMO) plays a very important role on the way of tryptophan catabolism through kynurenine pathway and has a definite regulatory effect on peripheral inflammation and central nervous system diseases." (PMID 32148781, 2020).
CNS tumors (1 paper, 2022). "KMO, the other enzyme that can take KYN as a substrate and produce 3-HK, showed a decreased expression in all CNS tumors which were evaluated compared to the brain cortex levels." (PMID 36355137, 2022).
digestive system tumors (1 paper, 2024). "KMO, a crucial enzyme in Trp metabolism, represents a rate-limiting step in this pathway and is implicated in the development of various digestive system tumors." (PMID 38462620, 2024). "Slower research progress is observed on KMO inhibitors compared to IDO/TDO inhibitors, possibly due to the complex role and regulatory mechanisms of KMO, requiring further research to understand its specific role in digestive system tumors." (PMID 38462620, 2024). "However, recent studies underscore KMO as a promising therapeutic target in digestive system tumors." (PMID 38462620, 2024).
inflammation (1 paper, 2025). Aberrant reaction of the microcirculation characterized by movement of fluid and leukocytes from the blood into extravascular tissues. "However, with age-related chronic inflammation, pro-inflammatory cytokines such as IFN-γ, IL-6, and TNF-α activate the KP by upregulating IDO and KMO and channeling TRP and KYN into the KMO branch shifting the KP toward oxidative metabolism." (PMID 41294839, 2025).
KMO also shares sentences with these, for which no sentence is quoted: brain diseases (2 papers); kidney failure (2); Multiple Organ Failure (2); autism spectrum disorder (1); benign tumors (1); brain injury (1); chronic renal failure (1); Cluster headache (1); COVID-19 (1); cutaneous squamous cell carcinoma (1); disorders of the immune system (1); ductal breast carcinoma in situ (1); Dystonia (1); hyperthyroidism (1); infectious disease (1); invasive lobular breast carcinoma (1); kidney damage (1); lobular breast carcinoma (1); lung carcinoma (1); metabolic disorders (1); multiple sclerosis (1); myocardial infarction (1); myocarditis (1); Parkinsonism (1); pseudoexfoliation syndrome (1); psychosis (1); renal failure (1); Seizure (1); Sepsis (1); thyroid carcinoma (1).
A further 1 disease shares a sentence with KMO in 1 paper.